CD4 (CD4 molecule)
Diseases named in the same sentence as CD4 in open-access papers (continued):
Sharing a sentence is not in itself a finding about the gene and the disease.
lung cancer (continued). "In addition, there are also identifying markers of early response in lung cancer, such as the TCR repertoire, the CD4+/CD8+ T cell profile, the cytokine signature, and immune checkpoint molecule expression in tumour cells, macrophages or T cells." (PMID 31729963, 2019). "In contrast, patients with dysfunctional systemic CD4 immunity did not respond even though they had lung cancer‐specific T cells." (PMID 31273938, 2019). "In addition, when sarcoidosis was compared with lung cancer, the CD4/CD8 ratio was much higher in sarcoidosis, and the CD3/CD19 ratio was higher in lung cancer indicating a marked difference in the immune system in both diseases." (PMID 30452447, 2018). "Although CD4+CD8+ DP T cells represented less than 2% of T cells in a majority of tumor samples, frequencies of CD4+CD8+ DP T cells above 5% of T cells were observed in 6/21 of RCC samples, 1/16 lung cancer and 1/16 CRC samples." (PMID 30534127, 2018). "In lung cancer tissue, increased levels of TSLP appear to be involved in the marked prevalence of immunosuppressive CD4+CD25+ Treg cells, which might help tumor cells escape the host immune system." (PMID 30214685, 2018). "The role of CD8+ T cells in anticancer immunity is well established, however, it is currently not clear if CD4+ T cells induced by DC-based HHP lung cancer vaccine can contribute to or mediate significant anti-tumor effect." (PMID 28187172, 2017). "DC-based HHP lung cancer vaccine exhibited functional plasticity after additional stimulation in serum containing medium with LPS or CD40L and was fully competent to stimulate CD8+ and CD4+ T cells." (PMID 28187172, 2017). "Moreover, using DC-based HHP lung cancer vaccine generated from NSCLC patients we observed an increase in proliferation and IFN-γ production in CD8+ and CD4+ T cells over the T cells stimulated with patient’s DC-treated with poly(I:C) only." (PMID 28187172, 2017). "Our study suggests that interaction between lung cancer cells and CD4+ T cells induces DNMT expression and IFNG promoter hypermethylation in CD4+ T cell, which may serve as an important mechanism of tumor-induced immunosuppression." (PMID 24244422, 2013). "We have found that TIM-3 is expressed in both CD4+ and CD8+ TILs in lung cancer tissues." (PMID 22363469, 2012). "The negative correlation of PYGB with these CD4+ T cell subsets might indicated a suppression of helper T cell functions, which could impair the overall immune response to lung cancer." (PMID 40458414, 2025). "However, elevated CD3/CD4 and NK-cell counts, together with a low NLR, may indicate improved clinical outcomes in lung cancer." (PMID 41446305, 2025). "Furthermore, no clinically meaningful impact on CD4+ T cell counts was observed in the presented studies on ICI treatment in people living with HIV with lung cancer." (PMID 41190419, 2025). "Research suggests that combining cryoablation with a traditional Chinese lung-nourishing formula may decrease CD4+ CD25+ Foxp3+ Treg cell proportions in the spleen and reduce Foxp3 expression in tumor tissues, thereby inhibiting Lewis lung cancer proliferation." (PMID 41438510, 2025). "Importantly, AP-2 transcription factors in lung cancer show significant correlations with immune cell infiltration, including CD8+ T cells, CD4+ T cells, and other tumor-infiltrating immune populations, suggesting potential mechanistic links between transcriptional regulation and immune modulation." (PMID 41373739, 2025). "Importantly, immune cell infiltrates of resected tumors from patients with MPR contained fewer CD16+ neutrophil granulocytes, CD14+ monocytes and CD4+CD25+ regulatory T cells compared with resected lung cancers without MPR." (PMID 38689060, 2024). "In addition, in lung cancer, MHC-II+ CAFs enhanced CD4+ T cell cancer immunity." (PMID 39575252, 2024).
lung cancer (continued). "CD4+ Th cells, the cells primary infected by HIV, have been hypothesized to be correlated with HIV-promoted lung cancer, while several studies have found that the immunosuppression determined by decreased CD4+ Th cells only showed a limited association with lung cancer incidence." (PMID 38542056, 2024). "Several studies have also reported that the CD4+/CD25(high)/FoxP3+/CD127- Tregs content is related to the prognosis of lung cancer patients, and the number of Tregs in the bronchoalveolar lavage fluid of patients with lung cancer has been found to be higher than that of patients with benign lesions." (PMID 38475858, 2024). "What’s more, growing studies have reported that the immune-related features of cancers such as the intensity of CD4+ T cells and CD8+ T cell infiltrates, macrophages, and natural killer (NK) cells, different B cell sub-populations were correlated with immunotherapeutic responsiveness in lung cancer." (PMID 36923797, 2023). "The interaction between CD4+ T follicular helper and B cells plays an important role in the induction of antitumor immune responses and may enhance the effector function of tumor-infiltrating CD8+ T cells in lung cancer." (PMID 35321241, 2022). "However, we found that co-culture of T cells from either WT or CXCR6-/- mice with ORFV NA1/11-infected lung cancer cells greatly affected CD4 T cell migration regardless of their sources." (PMID 35959371, 2022). "Co-culturing SPC-A1 lung cancer cells and healthy CD4+ T cells induced DNMT expression and IFNγ promoter hypermethylation in CD4+ T cells, indicating a tumor-induced, DNA methylation-dependent suppression of IFNγ in lung cancer and highlighting the crosstalk between these processes." (PMID 34901003, 2021). "Moreover, studies in lung cancer suggested that the CD8/CD4 ratio in patients in the non-metastasis group was remarkably higher, and these patients had a significantly better overall survival rate than patients with a low CD8/CD4 ratio." (PMID 32758195, 2020). "As both responders and non‐responders contained comparable proportions of lung cancer‐specific CD4 and CD8 T cells in our cohort of patients before the start of therapy, the experimental evidence pointed to the baseline intrinsic functionality of CD4 immunity as the key factor in our study." (PMID 31273938, 2019). "Indeed, studies have reported incremental changes to biomarkers of immunosenescence following repeated administration of chemotherapy, including lower ratios of CD4+ T cells to CD8+ T cells and accumulations of CD28− and CD57+ cells in patients with breast and lung cancer." (PMID 28751932, 2017). "In our study we showed that DC-based lung cancer vaccine generated in GMP-complaint serum free media with HHP-killed lung cancer cell lines and poly(I:C) exhibits functional plasticity and activity to stimulate tumor antigen-specific IFN-γ-producing CD8+ and CD4+ T cells from NSCLC patients." (PMID 28187172, 2017). "The proportion of CD4+/CD25high/Foxp3+/CD127- Tregs determined by flow cytometry and the proportion of Tregs with expression of (in)CTLA-4 were significantly elevated in the BALF harvested from the lung affected by lung cancer when compared with the last two compartments." (PMID 27866241, 2017). "The results showed increased number of both CD3+CD4+ and CD3+CD8+ T cells in spleen and tumor tissues in 3LL/shCXCL1 group compared to 3LL/NC control group, suggesting that the higher density of neutrophils was paralleled with the decreased T cells number in lung cancer." (PMID 27446967, 2016). "While T cells as source of IL-22 in lung cancer have not been proposed prior to our study, our data are supported by evidence from other tumor types such as colon, gastric or hepatic carcinomas where CD4 T cells are thought to be the main sources of IL-22." (PMID 27388918, 2016).
lung cancer (continued). "We also found that the proportion of CD3+ CD4+ T cells decreased significantly in colon cancer, primary liver cancer and lung cancer (p < 0.05), while the percentage of CD3+ CD8+ T cells increased significantly in primary liver cancer and lung cancer (p < 0.05)." (PMID 26561538, 2015). "Indeed, we report for the first time the major reductions not only in total CD4 and CD8 T cell and it mediated cell immune response but also in Tregs and CD4 memory T cells subsets, in response to the co-stimulation from both MTB antigen and lung cancer antigen." (PMID 30718463, 2019). "More importantly, to evaluate whether lung cancer cells could impact the methylation status of immune cells by down regulating IFNG expression, we established an in vitro transwell culturing system and then investigated CpG methylation of the IFNG promoter in CD4+ T cells." (PMID 24244422, 2013). "In lung cancer, glioma, HNC, and CRC patients, fencing of CD4+ T cells (not including Tregs) occurred more often than CD8+ T cell fencing." (PMID 41446806, 2025). "The proportion of CD4+/CD3+/CD25+/FoxP3+ CD4+ Treg cells and CD8+/CD3+/CD25+/FoxP3+ regulatory CD8+ Treg cells were significantly elevated in all the lung cancer patients before surgery, but not in the RFC group after surgery." (PMID 37238744, 2023). "CD4 count was the most important prognostic factor for mortality due to all, viral, and nonviral NADC, including lung cancer." (PMID 38008809, 2023). "The aim of this study was to determine the dominant subtypes of CD4+ and CD8+ lymphocytes in metastatic and non-metastatic LNs of lung cancer patients." (PMID 35585972, 2022). "On the contrary, in the pleural cavity of patients with lung cancer without MPE, the number of CD4+T cells was significantly lower than that of CD8+ T cells." (PMID 35794989, 2022). "ROC analysis was used to calculate the area under the curve (AUC) of CD8 T cell, CD4 T cell, CD16 + 56+, D-Dimer, and MFS in 143 NSCLC patients with stage III lung cancer (ATB, n = 47; non-ATB, n = 96)." (PMID 36384523, 2022). "The aim of the study was to determine the dominant subpopulation of CD4+ and CD8+ lymphocytes in metastatic and non-metastatic lymph nodes (LNs) of lung cancer patients." (PMID 35585972, 2022). "Our data has not demonstrated a significant difference in CD4 + CD25 + Treg abundance between toxicity and NT patients with lung cancer." (PMID 35672305, 2022). "These authors demonstrate that Tim3 expression on CD4 T cells but not on CD8+ T cells correlated with the presence of nodal metastases and advanced lung cancer stage." (PMID 32808188, 2021). "In a preclinical model of mice bearing lung carcinoma, paclitaxel has been demonstrated to selectively inhibit CD4+FOXP3+ Treg cells, but not other CD4+FOXP3- T helper cells." (PMID 33276524, 2020). "For instance, downregulation of CD3ε but not CD3ζ expression in CD4+ and CD8+ T cells has been reported in patient with lung carcinomas." (PMID 29951063, 2018). "Our results showed that acupoint stimulation has immunomodulatory effect for lung cancer patients, which was demonstrated by a significant increase of IL-2, CD3+ and CD4+ T cells, NK cells, but not CD8+ T cells." (PMID 24344728, 2013). "Our study showed that acupoint stimulation has strong immunomodulatory effect for lung cancer patients as demonstrated by the significant increase of IL-2, T cell subtypes (CD3+ and CD4+, but not CD8+ cells), and natural killer cells." (PMID 24344728, 2013). "In lung cancer patients, the median density values of WBC and lymphocytes, the frequency of lymphocytes and CD3+ T, CD4+ T, and CD8+ T cells, were at the lower boundary of the normal range, and lower than those in the healthy individuals, but not significantly different (p < 0.05)." (PMID 36901716, 2023). "Similarly, a higher percentage of platelets in both CD4+ PTCAs and CD8+ PTCAs were activated compared to free platelets in both healthy volunteers and lung cancer patients (not shown)." (PMID 32776968, 2020).
lung cancer (continued). "First, we found that in a mouse model of erlotinib-resistant lung cancer in which tumors do not regress upon treatment with the TKI, low numbers and functionally impaired CD4 and CD8 lymphocytes are found similar to untreated tumors even following TKI treatment." (PMID 31291990, 2019). "Previously we have demonstrated that ex vivo expanded human peripheral blood T cells expressing CD3, without CD4, CD8, and NK T cell marker expression, termed double negative T (DNT) cells, have potent activity against lung cancer and leukemia cells in patient-derived xenograft (PDX) models." (PMID 30857561, 2019). "The CD4/CD8 ratio was lower in T cells at resistance in both patients, as it was the case for the mouse EGFR TL and Kras lung cancer models In the anti-PD-1-resistant samples, we noted increased effector memory CD8 T cells (CCR7−CD45RA−) as compared with untreated samples." (PMID 26883990, 2016). "However, no apoptosis of CD4+ and CD8+ T-cells from lung cancer patients was observed after treatment with agonistic anti-Fas antibodies." (PMID 23118782, 2012). "Flow cytometry was used to measure the percentages of lymphocyte subsets (CD3+, CD4+, CD8+, CD4+/CD8+, CD19+, CD25+, CD44+, and NK cells) in peripheral blood obtained from 221 patients with primary lung cancer without any treatment and from 96 healthy blood donors as the control group." (PMID 21859548, 2011). "Overall, these data from human lung cancer samples that have not been treated with KRAS inhibitory drugs suggest that cellular communities similar to the mouse T/DC community exist at baseline, where CD4+and CD8+ T cells, DCs, and Tregs were gathered together at the tumor periphery." (PMID 39485838, 2024). "Similarly, the expression of BTLA was increased on CD4+ T cells and CD8+ T cells isolated from pleural effusion of lung cancer patients, indicating BTLA might mediate a negative cosignal for local immune response." (PMID 34163466, 2021).
psoriasis (436 papers, 2008 to 2026). An autoimmune condition characterized by red, well-delineated plaques with silvery scales that are usually on the extensor surfaces and scalp. "Frequencies of effector memory CD4+ T cells, Th17, and Tc17 cells differed among patients with psoriasis with at least one risk factor for transition, subclinical psoriatic arthritis, and psoriatic arthritis." (PMID 40955716, 2025). "This is of high significance in psoriasis because it explains how both LL37 and carb-LL37 skew the CD4 T-cell response towards a T-helper response that is pathogenic in psoriasis." (PMID 40270954, 2025). "Last, we outline how preventing PD-L1:CD80 interactions or mutating the PD-L1 cytoplasmic domain in a model of psoriasis limits DC migration, interleukin-17 (IL-17) production by CD4+ T cells, and epidermal thickening associated with disease." (PMID 39879305, 2025). "The upregulation of exhaustion markers TIM-3 and PD-1 on CD4+ T cells in recurrent psoriasis-like conditions indicates an exhausted phenotype linked to chronic activation which has been previously implicated in chronic inflammatory states." (PMID 40599782, 2025). "The authors propose that HIV disrupts the typical latitude-associated psoriasis risk pathway by directly interfering with CD4+ lymphocyte function." (PMID 41207052, 2025). "Kaempferol also reduced the proportion of IL-17A + CD4+ T cells in the spleen and lymph nodes of mice with psoriasis caused by IMQ." (PMID 39296901, 2024). "The production of IL-17A and IL-22, key inflammatory cytokines that are heavily implicated in the pathogenic of psoriasis, by CD4+ T cells has marked CD4+ T cells as a main target of research." (PMID 38067173, 2023). "miR-125a-5p was downregulated in peripheral blood CD4+ T cells of psoriatic patients, which was positively associated with the proportion of regulatory T cells (Tregs) and negatively correlated with the Psoriasis Area and Severity Index (PASI) score." (PMID 37773129, 2023). "The development of psoriasis is significantly influenced by the overactivation of CD4+ T cells, with Th17 and Th1 cells polarizing as the major pathogenic cells in psoriasis." (PMID 38239345, 2023). "Recently, a new population of IL-17-producing CD4+ Th cells, known as Th17 cells, along with their associated downstream effector molecules, has been found to be elevated in the skin of psoriasis patients." (PMID 38239345, 2023). "The pathophysiological mechanisms underlying psoriasis and PsA are not yet fully understood, but there is evidence pointing towards epigenetic dysregulation involving CD4+ and CD8+ T-cells." (PMID 37662940, 2023). "Several studies reported that CD4+ T cells were crucial for initiating and maintaining the pathogenic process of psoriasis." (PMID 35069008, 2022). "The ratio of CD4+/CD8+αβT cells is positively related with Koebner phenomenon caused by scratching in psoriasis." (PMID 35069008, 2022). "Psoriasis is a common chronic inflammatory disease caused by excessive activation of CD4+T cells, including Th17, Th1 and Th22." (PMID 35663772, 2021). "We identified lymphoid cells (CD4+Th1, CD4+Treg, and NK) and their associated pathways to be important in HLA-B27 type diseases (psoriasis, AS, and IBDs) and in primary-joint-inflammation-based inflammatory arthritis (AS and RA)." (PMID 34108969, 2021). "For example, DP T-cells that arise from CD8+ T-cells have improved cytotoxic functions, while DP T-cells that arise from CD4+ T-cells are associated with inflammatory conditions, such as psoriasis and multiple sclerosis." (PMID 34106915, 2021). "It has been reported that in psoriasis patients, ex vivo stimulation of dermal cell suspensions shows the presence of Th17 cells with the pathogenic phenotype (CD4+ IL-17+ IFN-γ+)." (PMID 32801996, 2020).